INS (insulin)
Diseases named in the same sentence as INS in open-access papers (continued):
Sharing a sentence is not in itself a finding about the gene and the disease.
Hypoglycemia (continued). "Reactive hypoglycaemia observed after HC meal was most likely related to increased secretion of insulin in response to the significant amount of ingested carbohydrates." (PMID 26609520, 2015). "Hypoglycaemia was prevalent amongst those on insulin; for mild/moderate episodes the prevalence was 50% and incidence 23 events per person-year, and for severe episodes the prevalence was 21% and incidence 1 event per person-year." (PMID 26061690, 2015). "His poor glycemic control was not a compliance issue but was due to frequent, severe, and unpredictable hypoglycemia that occurred whenever the dose of insulin was increased which resulted in underdosing of both his long- and short-acting insulins." (PMID 25785209, 2015). "In HH, an inappropriate insulin and/or C-peptide concentration will be detected at the time of hypoglycaemia, with simultaneous poor response of ketone bodies and plasma non-esterified free fatty acids." (PMID 26316429, 2015). "Glucagon nasal powder (GNP), a novel intranasal formulation of glucagon being developed to treat insulin-induced severe hypoglycemia, contains synthetic glucagon (10 % w/w), beta-cyclodextrin, and dodecylphosphocholine." (PMID 26502880, 2015). "β-cells have evolved important metabolic features to avoid excessive insulin secretion and hypoglycemia, particularly during exercise." (PMID 25982967, 2015). "She continued insulin at home but presented with multiple episodes of hypoglycemia 5 months later and insulin was stopped." (PMID 26966489, 2015). "The suppression of glucagon by GLP-1 declines towards normoglycemia, as does its effect on insulin secretion; together these mechanisms prevent hypoglycemia." (PMID 28702223, 2015). "The density of moderate hypoglycemia was 0.26 events per day of insulin therapy and 0.13 events per day in the ICU." (PMID 25888011, 2015). "Two patients, both in the NPH insulin group, reported events that fulfilled the criteria for severe hypoglycemia (0.6 % in the NPH insulin group)." (PMID 26055391, 2015). "Given the persistent hypoglycemia, history of polysubstance use, and suicidality, coingestion of sulfonylureas or possibly insulin administration was entertained and insulin and C-peptide levels were measured." (PMID 25692049, 2015). "The insulin infusion rate, time for which insulin infusion was withheld and mean blood glucose during hypoglycemia was significantly high in RHI group." (PMID 25874191, 2015). "Incidence of hypoglycemia was significantly reduced in the Ins+Sita group compared with the Insulin group." (PMID 25816296, 2015). "In order to avoid a too fast decrease of blood glucose levels throughout the course of the experiment, we induced hypoglycemia by repetitive administrations of insulin." (PMID 26564063, 2015). "Particularly among routine medical treatments, it is important to ask them regarding hypoglycemia during each visit, when patients are using insulin and SU agents." (PMID 26566411, 2015). "Secondary endpoints included serum glycoalbumin level, daily dose of insulin, intraday glycaemic variability and frequency of severe hypoglycaemia." (PMID 26044206, 2015). "The present case was examined with the findings of hypoglycemia and hypercalcemia, and as there was high insulin and C-peptide levels the initial diagnosis was insulinoma." (PMID 26295000, 2015). "Problematic hypoglycaemia is a significant problem among people with insulin-treated type 1 and 2 diabetes mellitus, which adversely affects quality of life and leads to high societal costs." (PMID 26292674, 2015). "Greater rates of hypoglycemia in patients receiving NPH insulin in comparison to insulin glargine have been reported in a similar magnitude in other trials." (PMID 26055391, 2015). "In order to avoid hypoglycemia during and after exercise, the dose of both basal long-acting insulin and short-acting insulin, as well as the choice of exercise intensity and duration, is of high relevance and must be balanced." (PMID 26317981, 2015).
Hypoglycemia (continued). "Randomized studies showed that a basal bolus regimen with insulin analogues resulted in equivalent glycemic control and frequency of hypoglycemia compared to treatment with human insulin." (PMID 26697118, 2015). "While NPH insulin has been shown to effectively reduce blood glucose levels, its peak in activity at around 4–6 h after administration can result in hypoglycemia." (PMID 26055391, 2015). "In contrast, we found lower incidence of hypoglycemia even in patients treated with sitagliptin-SU and sitagliptin-insulin, although the incidence was higher in dual therapy than in sitagliptin monotherapy." (PMID 25699116, 2015). "This study shows that simple nurse-managed preventive measures significantly reduced hypoglycemia in diabetic hospitalized patients treated with s.c. insulin." (PMID 25961051, 2015). "In addition to impaired hormonal counterregulation, people with CKD may have other risk factors for hypoglycemia, such as altered drug metabolism, albuminuria, malnutrition, impaired renal glucose release and insulin clearance, and dialysis associated problems." (PMID 26239457, 2015). "Numbers of hypoglycemic events per patient year of insulin treatment resulted in comparable rates of hypoglycemia in either group, confirmed by blood glucose thresholds of <3.1 and <3.9 mmol/L." (PMID 26055391, 2015). "There were also more hypoglycemia (when used in combination with insulin or insulin secretagogues) and more gastrointestinal side effects in this patient population." (PMID 26239457, 2015). "Significantly less neonatal hypoglycemia was found in metformin plus insulin group, P ≤ 0.01, and mean blood glucose levels at birth were also better in metformin plus insulin group." (PMID 25874236, 2015). "Insulin-induced hypoglycemia stimulates the release of serotonin in widespread forebrain regions, including the perifornical, ventromedial, and paraventricular hypothalamus, and induces food consumption." (PMID 26124826, 2015). "In case 2 a decreased utilization of short-acting insulin resulted in a lower frequency and severity of hypoglycemia which improved glycemic control." (PMID 25785209, 2015). "The number of patients on monotherapy who experienced hypoglycemia was only two (2.4%), while a higher percentage of patients who received the combination of sitagliptin and SU or insulin tended to experience hypoglycemia (about 75% and 31%, respectively)." (PMID 25699116, 2015). "High doses of exogenous insulin are required to induce hypoglycemia and chickens resist huge doses of exogenous insulin, which are lethal in mammals." (PMID 26431526, 2015). "Hypoglycemia is one of the most undesirable and unpredictable side-effects in insulin-treated diabetic patients." (PMID 26102197, 2015). "Four patients were excluded: 2 because their insulin requirements were <2 units/kg/d, 1 because consent was withdrawn, and the fourth because there was history of cirrhosis and severe hypoglycemia." (PMID 26222846, 2015). "Overall there are no major differences in the effects on glycemic control, but there can be differences in weight effects, hypoglycemia and insulin doses as well as in persistence." (PMID 28702235, 2015). "A common suggestion to prevent hypoglycemia is reduction of the insulin dose, although the improved glycemic profile is often obtained at the cost of a high glycemia before the effort." (PMID 25918842, 2015). "Patients receiving insulin therapy were significantly more prevalent among those with previous reported hypoglycemia (P = 0.009)." (PMID 26425567, 2015). "Data on its relationship in African children with severe malaria are relatively few, but what does exist indicates that insulin levels are appropriately low during episodes of hypoglycaemia, either at admission or during quinine treatment." (PMID 25858094, 2015). "In order to avoid hypoglycemia, readjustments in the insulin regimen were considered if BG levels decline below 100 mg/dL (5.6 mmol/L)." (PMID 26697118, 2015).
Hypoglycemia (continued). "The reported incidence of hypoglycemia was 5.6-10% in sitagliptin-SU combination therapy and 16-20.2% in sitagliptin-insulin combination." (PMID 25699116, 2015). "The patient developed autoantibodies that inhibited the binding of insulin to the erythrocyte's receptors and stimulated the insulin receptor leading to hypoglycemia." (PMID 26839722, 2015). "This study is the first to assess both the short-term and long-term regulation of adrenal TH enzyme activity following prior exposure to insulin-induced hypoglycemia in normal rats." (PMID 25713330, 2015). "After cessation of insulin, hypoglycemia was still observed recurrently during hospitalization, although it improved generally in these patients in the present study." (PMID 25961056, 2015). "During an observed fast he developed hypoglycemia at six hours with insulin levels 100 times and proinsulin levels 40 times normal." (PMID 26241232, 2015). "After a median time of 5 months (IQR, 4–12) from the initiation of insulin therapy, unexpected hypoglycemia occurred recurrently in these patients even after discontinued insulin therapy." (PMID 25961056, 2015). "Regarding monotherapy, hypoglycemia was observed in 32.7% of the patients with insulin, 4% in sulfonylurea (SU), 3.8% in glinide, and 3.5% in pioglitazone." (PMID 26566411, 2015). "Incidence of any hypoglycaemia was lowest in patients receiving to Met/Incr (6.5%) and it was substantially higher in those receiving Met/SU (15.4%; OR 2.70; 95% CI 1.48–4.92) or insulin (37.1%; OR 8.35; 95% CI 4.84–14.4)." (PMID 25645672, 2015). "In several cases the severity of the hypoglycemia and the level of insulin antibodies closely paralleled the remission–relapse pattern of the myeloma and the level of the monoclonal immunoglobulin." (PMID 26241232, 2015). "In 2012, the proportion of hypoglycemia admissions per 1000 diabetic patients was 2.1, and the proportion of hypoglycemia admissions per 1000 diabetic patients receiving insulin and/or oral hypoglycemic agents was 4.1." (PMID 26107672, 2015). "Hypoglycaemia in the early postprandial period is also a concern for low-CHO meals containing significant amounts of protein and/or fat, with patients often reporting hypoglycaemia soon after the meal when insulin is dosed upfront." (PMID 26202844, 2015). "It is well known that hypoglycemia is induced by various reasons such as the overuse of anti-diabetic drugs and/or insulin, various diseases including insulinoma, insulin autoimmune syndrome and adrenal insufficiency." (PMID 25918682, 2015). "Initiation of insulin does require patient education and support to recognise the clinical features of hypoglycaemia and more stringent monitoring." (PMID 26550039, 2015). "Apart from high HbA1c, patients with probable depression were twice more likely to report hypoglycemia than the non‐depressed group, even after adjustment for potential confounders, including disease duration, renal function, use of insulin and sulphonylurea." (PMID 25349949, 2015). "Mutations in the SLC16A1 gene that result in its aberrant expression in β-cells provoke exercise-induced hypoglycemia by enabling pyruvate-induced insulin secretion." (PMID 25982967, 2015). "In fact, among T2DM patients in higher BMI groups basal insulin doses were significantly greater; however the frequency of symptomatic hypoglycemia trended to decrease as BMI increased." (PMID 26594250, 2015). "When values are <50 mg/dL, or the patient has symptoms of hypoglycemia, a blood test is drawn for serum glucose, insulin, proinsulin, and C-peptide levels, and the fast is stopped." (PMID 25816027, 2015). "Neonatal complications like transient tachypnea of newborn, neonatal sepsis, neonatal intensive care unit stay, and neonatal hypoglycemia were found significantly less in metformin treated group when compared with insulin group." (PMID 25874236, 2015).
Hypoglycemia (continued). "The density of severe hypoglycemia was 0.037 events per day of insulin therapy and 0.020 events per day in the ICU." (PMID 25888011, 2015). "Hypoglycemia and enhanced whole body insulin sensitivity are additional limitations in the MCD diet model." (PMID 24454937, 2014). "Insulin type was identified as an independent predictor of the occurrence of one or more episodes of hypoglycaemia during the study." (PMID 25048824, 2014). "It is necessary to document hypoglycemia during the test, as insulinoma demonstrates a too high insulin concentration in the face of hypoglycemia." (PMID 25202394, 2014). "The prospective, observational registry in Germany demonstrated that hypoglycemia is a frequent AE in insulin-naïve T2DM patients having insufficient glycemic control on OADs, and receiving intensified antidiabetic treatment." (PMID 24528773, 2014). "Age, presence of diabetic complications, and poor renal function were the predictors of hypoglycemia in insulin-naïve patients." (PMID 24528773, 2014). "In human medicine, it is well-known that digoxin therapy increases the adrenaline-induced, and attenuates the insulin-induced hypoglycaemia due to catecholamines release in the acute stage of the action of digitalis glycosides." (PMID 24621180, 2014). "The study also demonstrated, for the first time, that among insulin-naïve T2DM Japanese patients, hypoglycemia is associated with poor renal function." (PMID 24528773, 2014). "When the patient re-presented, it was due to the development of new symptoms classical of hypoglycaemia and with biochemistry typical of excess insulin production." (PMID 24683485, 2014). "We also identified events that required intervention to keep the patient alive, such as hypoglycemia, cardiac tamponade and over-sedation, related, respectively, to the use of insulin, heparin and midazolam." (PMID 25496209, 2014). "By extending this scenario, it is possible that SIR increases and buffers part of the circulating insulin, preventing the development of hypoglycemia in healthy subjects, in response to high insulin levels." (PMID 24995000, 2014). "In this case, anti-insulin antibodies interfered with the pharmacological action of administrated insulin resulting in hypoglycaemia and insulin resistance." (PMID 24711924, 2014). "In a recent randomized study, 47 pregnant women with GDM who received metformin or insulin therapy were evaluated, and metformin group had better daily glycemic control, lesser weight gain neonatal hypoglycemia." (PMID 28913014, 2014). "The general safety profile relating to hypoglycemia was similar in the two age cohorts; thus, suggesting that insulin lispro is a safe and effective treatment option for the geriatric population." (PMID 23959960, 2014). "Glyburide significantly increased the risk of macrosomia (RR, 3.07; 95% CI, 1.14–8.23, p-value = 0.03) and neonatal hypoglycemia (RR, 2.30; 95% CI, 1.28–4.11, p-value = 0.005) compared to insulin." (PMID 25302493, 2014). "In the HOE 901/3002 study, 33% of insulin-naïve patients receiving insulin glargine experienced at least one episode of symptomatic hypoglycemia, and 9.9% patients experienced nocturnal hypoglycemia." (PMID 24528773, 2014). "Evidence from early clinical presentation showed a gradual increase in insulin requirement and the concomitant rise in glucose concentrations over periods of days preceded a period of severe hypoglycaemia." (PMID 24711924, 2014). "In this study the HbA1c at the end of the first year was similarly, the rates of hypoglycemia was lowest in the basal insulin group." (PMID 24620742, 2014). "Adjusting the insulin dose for unexplained hypoglycemia was deemed necessary from a safety standpoint." (PMID 25024710, 2014). "In Nigeria, hypoglycemia was the most frequently documented problems encountered by persons on insulin." (PMID 24397956, 2014).
Hypoglycemia (continued). "The fasting state encourages the release of a large amount of the bound insulin and results in the nocturnal hypoglycaemia." (PMID 24711924, 2014). "In the current study, rate of hypoglycemia in insulin-naïve patients was 1.1%, which is higher than that reported in the earlier observational study." (PMID 24528773, 2014). "Despite subsequent reductions in glycaemia, and the administration of a second dose of rapid-acting insulin 60 minutes post-exercise, all patients under 50% were protected from hypoglycaemia throughout their laboratory stay." (PMID 24858952, 2014). "Hypoglycemia induced a rapid diminishment of insulin, as well as a rise in glucagon and pancreatic polypeptide levels." (PMID 24594704, 2014). "The definitions of hypoglycemia (<56 mg/dL or 3.1 mmol/L) are consistent with other studies involving insulin detemir, and is a level at which autonomic symptoms of hypoglycemia are known to occur." (PMID 25048824, 2014). "Atropine reduces basal levels of insulin and glucagon induced by hypoglycemia and intravenous injection of arginine, respectively." (PMID 24616659, 2014). "The practical implications of these findings are most importantly that GLP-1 preserves myocardial glucose metabolism during hypoglycemia in insulin resistant subjects." (PMID 24400077, 2014). "Such measures include, on one hand, hyperventilation and increased blood pressure to facilitate blood-borne O2 supply to organs and, on the other hand liver glycogenolysis and insulin resistance of peripheral tissues to combat hypoglycemia." (PMID 25360117, 2014). "The protective mechanisms against hypoglycemia include suppression of insulin secretion and rise of counterregulatory hormones, especially glucagon and epinephrine." (PMID 25177371, 2014). "In summary, we described the use of glycemic clamps to assess insulin sensitivity and entero-insular hormonal responses in response to hyper- and hypoglycemia in ferrets." (PMID 24594704, 2014). "Hypoglycemia is a common medical emergency in diabetic patients treated with insulin or oral hypoglycemic drugs." (PMID 24891941, 2014). "Serum insulin level turned out to be very high (>300 uIU/mL), while the C-peptide was low, suggesting factitious hypoglycemia." (PMID 25541899, 2014). "Insulin injection (acute hypoglycemia) decreased [Gluc]ECF similarly in the OB of the two rat strains." (PMID 25278856, 2014). "Patients said that in the short term, increasing the insulin dose led to a fear of developing hypoglycemia (“consequences”, Self-Regulatory Theory)." (PMID 25340869, 2014). "Additional triggering events leading to iatrogenic hypoglycemia include inappropriate timing of short- or rapid-acting insulin such as aspart and lispro in relation to meals." (PMID 24397956, 2014). "Serum samples obtained at the time of hypoglycemia showed low insulin (0.902 uIU/mL) and C-peptide levels (0.1 ng/mL)." (PMID 25541899, 2014). "Unfortunately, there was a relatively high occurrence of hypoglycemia among the patients despite strict insulin regulation and the relatively short duration of the experiment (compared to intensive insulin therapy)." (PMID 25278226, 2014). "Cases of factitious hypoglycemia due to surreptitious administration of insulin as well as of sulfonamides have been reported." (PMID 25541899, 2014). "HG + INS fetuses were infused for the final 7 days with exogenous insulin and glucose to maintain a 1 week fetal hyperinsulinemic‐hypoglycemia clamp." (PMID 24944291, 2014). "In summary, surreptitious administration of insulin should be considered as a possible scenario in diabetic patients with hypoglycemia." (PMID 25541899, 2014). "Serum samples obtained at the time of hypoglycemia were measured by two different commercial insulin assays with different sensitivity for insulin analogues." (PMID 25541899, 2014).